GPC3 (glypican 3)
Diseases named in the same sentence as GPC3 in open-access papers (continued):
Sharing a sentence is not in itself a finding about the gene and the disease.
tumor (continued). "The moderate correlation (rspearman>0.66) between ASGPR protein and EpCAM mRNA, GPC‐3 mRNA, and EpCAM protein implies that combining these biomarkers could provide a more comprehensive view of tumor progression, potentially improving HCC diagnostic efficacy." (PMID 39556692, 2025). "Additionally, bispecific CAR-T cells targeting both GPC3 and PD-1 reduce the risk of tumor escape while maintaining prolonged cytotoxicity against PD-L1-positive HCC cells." (PMID 40051497, 2025). "Furthermore, CD40L-actived B cells of HCC patients were able to induce in vitro CD4+ and CD8+ responses in autologous TIL fractions to tumour-associated antigens (glypican-3, MAGE-C2)." (PMID 38440738, 2024). "Moreover, some studies have demonstrated that glypican-3 (GPC3) was closely associated with tumor progression and acted as an oncogene in GC, which was consistent with our findings." (PMID 37908977, 2023). "Moreover, as a co-receptor in Wnt and HGF, GPC3 is found to promote the progression of tumor and to be associated with a poor prognosis in HCC." (PMID 38023195, 2023). "A series of tumour-specific antigens, such as Glypican 3 (GPC3), epidermal growth factor receptor variant III (EGFRvIII), c-Met, PD-L1, CD133, NK group 2 member D (NKG2D) ligands (NKG2DL) and some viral-derived cancer antigens, have been explored and used to construct CAR-T cells against HCC." (PMID 37635247, 2023). "We believed that GPC3 may act as a tumor-related specific antigen in the immunotherapy of LUSC causing the recognition of DC that can present the recognized antigen information to the initial T cells to generate specific CTL for antitumor killing." (PMID 37965271, 2023). "Aside from ICIs, new therapeutic approaches target tumor-specific antigens (TSA: antigens only expressed by tumor cells) and tumor-associated antigens (TAA: antigens overexpressed by tumor cells but also expressed by healthy cells) such as glypican-3 (GPC3) or alpha-fetoprotein (AFP)." (PMID 36139683, 2022). "The correlations between CDCA2 protein expression and the clinicopathological characteristics of the patients were analyzed, and the results showed an association of high CDCA2 protein expression with high tumor grade (P = 0.0405) and Glypican-3 positivity (P = 0.049)." (PMID 35694386, 2022). "The use of nanoparticles conjugated with anti-GPC3 agents may improve drug delivery, leading to a reduction in severe side effects caused by chemotherapy and increased drug release at the tumor site." (PMID 36077433, 2022). "Peptide vaccines exploit tumor-associated antigens, such as α-FP, GPC3, and TERT." (PMID 34440678, 2021). "Overexpression of GPC3 in the cell membrane can induce M2-polarized tumor-associated macrophages to enter human HCC tissues that may stimulate the progression and metastasis of HCC." (PMID 34306031, 2021). "NK cells target tumor cells sensitized by monoclonal antibodies specific for tumor associated antigens GPC-3 or AFFP on tumor cells by mediating ADCC and this would also be a promising therapeutic strategy after activation of NK cells with cytokines such as IL-15." (PMID 34071188, 2021). "GPC3 overexpression has been associated with increased tumor growth and metastatic ability." (PMID 32582830, 2020). "On the other hand, partial clinical data on GPC-3 based vaccines demonstrated that the vaccine could induce measurable anti-tumor responses and are associated with prolonged OS of HCC patients." (PMID 31500650, 2019). "Recently, an association between the expression of GPC3 and glucose metabolism has been observed in the tumor tissues of LC patients, indicating that GPC3 may play a role in the regulation of glucose metabolism in LC cells." (PMID 31781603, 2019). "Membrane overexpression of GPC3 recruits M2-polarized tumor-associated macrophages (TAM) into human HCC tissues, which may promote HCC progression and metastasis." (PMID 29535817, 2018).
tumor (continued). "Moreover, PD-1-deficient GPC3-CAR T cells showed stronger anti-tumor activity compared with the wild-type GPC3-CAR T cells." (PMID 30327605, 2018). "Meanwhile, the anti-tumor activity of PD-1 deficient GPC3-CAR T cells against GPC3-negative SK-HEP-1 HCC cells was limited (<5%) and similar to that of UTD and wild-type GPC3-CAR T cells, indicating that the disruption of PD-1 did not affected the cytotoxic specificity of GPC3-CAR T cells." (PMID 30327605, 2018). "In another experiment, T cells with two complementary CARs against GPC3 and asialoglycoprotein receptor 1 (ASGR1) decreased the risk of on-target, off-tumor toxicities and demonstrated potent antitumor immune responses targeting GPC3+ ASGR1+ HCCs both in vivo and in vitro." (PMID 29785403, 2018). "αFP and glypican-3 (GPC3) are the main HCC tumor associated antigens of peptide-based vaccine." (PMID 28420805, 2017). "However, there was significant association between lower levels of GPC3 and higher number of distant metastases (P=0.039), depth of invasion (P=0.019), and tumor spread to the lymph nodes (P=0.015) (n=51, 31 cases of Beijing cohort, 20 cases of Wuhan cohort)." (PMID 27259271, 2016). "GPC3 is a cell surface protein that has been implicated as a possible tumor marker for HCC." (PMID 24980149, 2014). "Glypican-3(GPC3) has been implicated in tumor development and progression for several years." (PMID 24548704, 2014). "Moreover, colorectal carcinoma-associated liver metastases express GPC3 significantly more than primary tumours." (PMID 15083193, 2004). "Moreover, leveraging GPC3 expression as a biomarker could guarantee a deeper knowledge of tumor biology—differentiation grade and vascular invasion risk—and guide theranostic strategies." (PMID 40722645, 2025). "GPC3 is expressed in placenta and endometrium, suggesting that female patients, especially pregnant patients, may have a high risk of “on-target off-tumor”." (PMID 35251989, 2022). "Similarly, another group verified that pretreatment the tumor by a recombinant adeno-associated virus carrying the CCL19 gene (AAV-CCL19) could increase the infiltration of GPC3 CAR-T to tumor tissue and significantly prolonged the survival time of mice." (PMID 36093115, 2022). "Thus, T cells carrying two complementary CARs against GPC3 and ASGR1 may reduce the risk of off-tumor toxicity while maintaining relatively potent antitumor activity on GPC3+ASGR1+ HCC." (PMID 34071188, 2021). "Finally, the marked inhibitory potential of DCs-GPC3-CIKs on HepG2-induced tumor growth may be associated with antitumor cytokines, such as IFN-γ." (PMID 25625609, 2015). "Following systemic administration, the nanoparticles high-specifically bind to GPC3-overexpressing tumor membranes and transform into surface-anchored nanofibrils, exposing confined DBCO groups." (PMID 42054448, 2026). "In vivo, GPC3 deletion markedly enhanced radiation-induced tumor growth delay in both HepG2 and A431 xenograft models." (PMID 42182336, 2026). "These markers provide a more direct indication of oncogenic activity and include Golgi protein 73 (GP73), glypican-3 (GPC3), osteopontin, circulating tumor DNA (ctDNA), and cell-free DNA (cfDNA)." (PMID 41514666, 2026). "Glypican-3 (GPC-3) serves as a critical therapeutic target in HCC due to its selective overexpression in tumour cells compared to normal adult liver tissues." (PMID 41503573, 2026). "GPC-3 promotes tumor growth by enhancing canonical Wnt/β-catenin signalling, leading to increased expression of oncogenes such as c-Myc and Cyclin D1." (PMID 41511652, 2026). "Stemness-associated genes such as GDF15, ALDH1L1, GPC3, AFP, EPCAM, CD44, and CD24 were predominantly expressed in tumor cells, with varying levels across other cell types including CAFs, TECs, and TAMs." (PMID 41493679, 2026).
tumor (continued). "The resulting compound was labeled with both 18F and 68Ga in murine HCC models and the dual-imaging probe achieved tumor uptakes 30–60% higher than monomeric GPC3 or PSMA tracers, with tumor-to-muscle ratios exceeding 4:1 at 90 min post-injection." (PMID 40722645, 2025). "Lastly, what exceeded our expectations is that adding GPC3-targeting immunotoxins into OHSV2-DSTEFAP5/CD3 and GPC3-targeting CAR T cells group resulted in a significant increase in the killing effect on tumor cells." (PMID 40406146, 2025). "Various therapeutic modalities targeting GPC3 have been developed, leveraging its accessibility on the tumor cell surface." (PMID 40722645, 2025). "Affibodies and aptamers, for instance, exhibit the potential of combining nanomolar affinities for GPC3 with minimal immunogenicity, and their small size promises even more rapid blood clearance and tumor penetration." (PMID 40722645, 2025). "Second, GPC3 expression heterogeneity in the tumor further complicates interpretation, with 15–20% of HCCs demonstrating intratumoral variability in GPC3 expression." (PMID 40941632, 2025). "We then administered 5 × 106 anti‐GPC3 CAR‐T (9F2) cells via portal vein injection on Day 7 post‐operation to mimic the treatment of small tumours representing early‐stage HCC and meanwhile, performed tail vein injection as a control for systemic delivery." (PMID 41267637, 2025). "Previous studies on multiple IL-15-based CAR-T therapies targeting GPC-3 or CLDN18.2 have primarily focused on directly attacking tumor cells." (PMID 41455698, 2025). "Liver- and tumor-associated markers, such as AADAC, CLRN3, GPC3, CD40, and ALB, were downregulated in LC4 cells compared to freshly isolated tumor core cells and parental tissues." (PMID 40431665, 2025). "Based on current knowledge, our study aimed to engineer primary CAR-NK cells to express the chimeric antigen receptor specific to the HCC-related tumor target Glypican-3." (PMID 41465318, 2025). "GPC3 acts as a critical function in the tumor proliferation, invasiveness, and deteriorative metastasis." (PMID 41438490, 2025). "The observed association between GPC3 expression and inferior survival aligns with preclinical and translational data implicating GPC3 in tumor growth, angiogenesis, and activation of oncogenic pathways such as WnWnt-catenin and IGF signaling." (PMID 41463223, 2025). "In contrast, GPC3 is expressed on the tumor cell surface in the majority of HCCs, offering a more direct avenue for both imaging and targeted radionuclide therapy." (PMID 40722645, 2025). "Belzupacap sarotalocan is a novel agent that combines tumor-targeting with photoactivation, selectively binding to cancer cells expressing glypican-3 (GPC3) and inducing cell death upon exposure to light from laser use." (PMID 40061902, 2025). "IGD NPs target HCC cells through GPC3, releasing heat and reactive oxygen species (ROS) under noninvasive 808 nm laser irradiation to reduce tumor size and achieve downstaging." (PMID 39866786, 2025). "To address this unmet need, we developed a bispecific antibody (BsAb) platform targeting CD16A on natural killer (NK) cells and glypican-3 (GPC3), a tumor-specific antigen overexpressed in 70% of HCC cases." (PMID 40574860, 2025). "In this study, we demonstrated the anti-tumor effects of GPC3-specific NK92MI/HN3 cells both in vitro and in vivo." (PMID 39841705, 2025). "In hepatobiliary cancers, especially HCC, glypican-3 (GPC3) is a promising antigen due to its high tumor specificity and minimal normal tissue expression." (PMID 40940995, 2025). "Histologically, the tumor showed hepatoid differentiation with positive immunohistochemical staining for AFP, HepPar-1, and GPC3, indicating a tumor profile highly reminiscent of liver cancer." (PMID 40430002, 2025). "So glypican-1 and glypican-6 serve largely as tumour promoters, and glypican-3, and glypican-4 inhibit BC." (PMID 41463344, 2025).
tumor (continued). "We observed similar results in our HepG2 subcutaneous tumour model, where anti‐GPC3 CAR‐T cells effectively eradicated the tumours via either intratumoural or tail vein injection routes." (PMID 41267637, 2025). "Tumor-associated antigens such as AFP and glypican-3 (GPC-3), which are highly expressed in tumor cells, are often targeted in specific immunotherapy for HCC." (PMID 40432108, 2025). "Most engineered ACT targets in HCC fall into three categories: tumor-associated or tumor-specific antigens (AFP, GPC-3), viral-derived antigens (HBV, HCV), and cancer-testis antigens (NY-ESO-1, MAGE)." (PMID 41041128, 2025). "These immunotherapeutic approaches aim to specifically target and eliminate GPC3-expressing tumor cells while minimizing off-tumor effects." (PMID 39841705, 2025). "The Apt‐Ce6‐PDA@Pt nanoformulation achieves active tumor targeting by specifically recognizing GPC3‐positive cancer cells through the aptamer, whereas PDA facilitates NIR absorption for efficient photothermal conversion." (PMID 41201063, 2025). "We found that NK92MI/HN3 cells, rather than NK92MI/HS20 cells, exhibited a significant cytotoxicity effect against GPC3+ HepG2 cells in vitro and efficiently suppressed tumor growth in a xenograft model using NSG mice." (PMID 39841705, 2025). "Confusingly, there are also some reports showing GPC3 to act as a tumor suppressor gene in certain tumor types where GPC3 is overexpressed and has been shown to play an oncogenic role." (PMID 40422229, 2025). "Alternative approaches have also identified that glypican-3 modulates the activity of the p38MAPK signalling pathway to the extent of inducing an EMT that would reverse the tumour cell phenotype and induce a reduced metastatic potential." (PMID 41463344, 2025). "GPC3-targeted imaging has the potential to fill this gap by offering a noninvasive surrogate for tumor aggressiveness, as biomarker expression levels have been correlated with malignancy and metastatic propensity." (PMID 40722645, 2025). "CAR-T cells are often targeted against over-expressed tumour antigens, such as the membrane-bound proteoglycan glypican 3 (GPC3), in the case of solid tumours, including RTs." (PMID 40422882, 2025). "In this setting, 5 × 106 anti‐GPC3 CAR‐T cells were administered on day 21 post‐implantation of tumour xenografts." (PMID 41267637, 2025). "Consistent with the in vitro assay, the CAR‐T treatments against GPC3+ xenografts constructed using HepG2 and Hep3B cells, via either p.v. or t.v. injections, demonstrated robust anti‐tumour efficacy." (PMID 41267637, 2025). "Immunohistochemical markers such as CK-7, Glypican 3, and TTF-1 showed significant diagnostic value between tumor subtypes." (PMID 40804826, 2025). "The results showed that the mRNA level of GPC3 was markedly increased in HCC and is also detectable in several other cancers, suggesting a broad-spectrum activity of GPC3 in tumor development." (PMID 39841705, 2025). "PD-L1 and Glypican-3 are key elements of the tumour microenvironment (TME) definition that depicts a complex interaction between tumour cells and other cell types, increasingly addressed as therapeutic target in HCC26–28." (PMID 40640280, 2025). "HIF-1α facilitates GPC3 loading into sEVs, reducing intracellular GPC3 to suppress Wnt/β-catenin signaling and tumor growth." (PMID 40703510, 2025). "PET images acquired 30 min p.i. showed tumor uptake and tumor-to-muscle (T/M) ratios comparable to those obtained by single GPC3-targeted radiopharmaceutical." (PMID 40869454, 2025). "PGCMNPs therapy was initiated after confirming the presence of tumor via blood serum marker (GPC-3)." (PMID 38990437, 2025). "Experimental evidence suggests that GPC3‐targeted CAR‐T cells are capable of inducing sustained tumor regression in murine models of HCC." (PMID 40060195, 2025).
tumor (continued). "Taken together, GPC3 can target the same signaling pathways to exert diametrically opposed effects, thereby promoting or inhibiting cancer progress in different tumor cells." (PMID 40422229, 2025). "In this study, we aimed to detect portal vein circulating tumor cells (CTCs) using a Glypican-3-positive detection method and evaluate their prognostic significance." (PMID 40924249, 2025). "Tumor growth studies further demonstrated that GPC3-targeted NPs exhibited the strongest tumor growth inhibition among all tested formulations." (PMID 40278256, 2025). "Together, these results indicate that GPC3 expression correlates with tumor differentiation and clinical outcomes in HCC." (PMID 40941632, 2025). "Future studies should therefore extend this bead-based approach by incorporating analyses of tumor-specific mutations or methylation patterns within HCC-related genes in cfDNA, or by evaluating additional protein markers (e.g., GPC3) in CTCs alongside AFP." (PMID 41002319, 2025). "GPC3 alterations impact several signaling pathways within the tumor microenvironment (TME), regulating tumor cell proliferation and immune responses." (PMID 40657181, 2025). "In vivo studies in mice bearing GPC3-positive xenografts confirmed sustained and tumor-specific uptake, accompanied by fast renal clearance and minimal off-target accumulation." (PMID 40722645, 2025). "Moving forward, combining GPC3-targeted MRI with therapy response biomarkers or imaging-guided biopsy could further enhance clinical decision-making by improving diagnostic accuracy and ensuring molecular characterization is obtained from the most relevant areas of the tumor." (PMID 41154412, 2025). "GPC3-targeted CAR-NK cells have shown robust anti-tumor activity both in vitro and in vivo, displaying efficient tumor infiltration, suppression of cancer cell proliferation, and induction of apoptosis." (PMID 41465318, 2025). "HS20, another human anti-GPC3 monoclonal antibody that binds to the molecule's HS moiety, has been demonstrated to suppress tumor growth and block Wnt signaling." (PMID 40416124, 2025). "The GPC3/CD47 bispecific antibody co-targets a tumor antigen and the “don’t eat me” signal, namely the CD47–SIRPα pathway." (PMID 41375072, 2025). "GPC3-targeted CAR T-cells have demonstrated anti-tumor activity in xenograft models and have now entered clinical testing." (PMID 40940995, 2025). "In a hepatocellular carcinoma model, GPC3-BBz CAR-T cells with RUNX3 overexpression exhibited better tumor control, with increased CAR-T cell numbers in blood and tumor tissue, along with a higher proportion of Tem cells." (PMID 40693464, 2025). "This approach was implemented using a novel nanocarrier system, where red blood cell membrane (RBCM)-coated NPs were further functionalized with the tumor-targeting peptide glypican-3 (GPC3) to achieve precise tumor-targeted delivery." (PMID 41345744, 2025). "Supporting this interpretation, GPC3 and c-MYC showed parallel upregulation in HCLs but not in HepaFH3 or PHHs, consistent with reports that c-MYC can transcriptionally upregulate GPC3 expression, reinforcing their potential combined value as tumor biomarkers." (PMID 40862732, 2025). "The subcellular localization of GPC3 expression within tumor cells also had prognostic implications." (PMID 41463223, 2025). "PET/CT showed a high tracer uptake in GPC3-positive lesions with rapid clearance from healthy liver, yielding excellent tumor-to-liver ratios (mean TLRmax 8.3; mean TLRmean 7.5 at ~1 h post-injection)." (PMID 40722645, 2025). "Recent advances in immunotherapy have brought Glypican-3 (GPC3) into focus as a prime therapeutic target - this heparan sulfate proteoglycan demonstrates tumor-specific overexpression in 70% of HCC cases while maintaining near absence in normal liver tissue." (PMID 40574860, 2025).